PLIN2 (perilipin 2)
Description:
Structural component of lipid droplets, which is required for the formation and maintenance of lipid storage droplets.
Synonyms: ADRP; ADFP
Tractability: Antibody: its Gene Ontology location is reachable by antibodies, with high confidence; UniProt places it where antibodies can reach, with medium confidence. PROTAC: UniProt records ubiquitination sites on it; ubiquitination databases record sites on it; its protein half-life has been measured.
Gene: Protein-coding gene on chromosome 9 (19,108,375 to 19,149,369, reverse strand). Ensembl gene ENSG00000147872.
Subcellular location: Membrane; Lipid droplet
Subcellular location (Human Protein Atlas): Lipid droplets
Pathways (Reactome):
Autophagy: Chaperone Mediated Autophagy; Late endosomal microautophagy; Lipophagy
Gene expression (Transcription): MLL4 and MLL3 complexes regulate expression of PPARG target genes in adipogenesis and hepatic steatosis
Metabolism: PPARA activates gene expression
Gene Ontology:
Molecular function: protein binding
Biological process: cellular response to glucose starvation; lipid droplet disassembly; lipid storage; positive regulation of triglyceride storage
Cellular component: lipid droplet; cytosol; endoplasmic reticulum; extracellular region; membrane; plasma membrane; cytoplasm; nucleus
Genetic constraint (gnomAD): Loss-of-function variants: 30 observed, 29.21 expected, observed/expected ratio (o/e) 1.03, 90% interval 0.77 to 1.39. The upper end of that interval is the gene's LOEUF score, 1.39, which puts it in group 5 of 6, group 1 being the genes least tolerant of losing a copy. Missense variants: 592 observed, 538.64 expected, observed/expected ratio (o/e) 1.1, 90% interval 1.03 to 1.18. Synonymous variants: 202 observed, 206.94 expected, observed/expected ratio (o/e) 0.98, 90% interval 0.87 to 1.1.
Homologues: Orthologues: macaque PLIN2 (97% identical), chimpanzee PLIN2 (92% identical), pig PLIN2 (86% identical), dog PLIN2 (86% identical), rabbit PLIN2 (83% identical), mouse Plin2 (80% identical), rat Plin2 (76% identical), tropical clawed frog plin2 (58% identical), zebrafish plin2 (53% identical), Drosophila melanogaster Lsd-2 (20% identical). Paralogues in human: PLIN3 (40% identical), PLIN5 (32% identical), PLIN4 (27% identical), PLIN1 (25% identical).
Diseases named in the same sentence as PLIN2 in open-access papers:
PLIN2 is named in the same sentence as 189 diseases in open-access papers, as found by Europe PMC text mining. Sharing a sentence is not in itself a finding about the gene and the disease. The quoted sentences say what the papers report.
Hepatic steatosis (88 papers, 2013 to 2025). Steatosis is a term used to denote lipid accumulation within hepatocytes. "In contrast, specific deficiency of either Plin2 or Plin5 reduces LD accumulation, ameliorates hepatic steatosis, and delays the progression of MASLD." (PMID 41373932, 2025). "SNX10 deficiency enhances the development of alcoholic fatty liver by decreasing the degradation of LAMP2A/PLIN2 in the liver." (PMID 40426851, 2025). "Several studies have reported the association between PLIN2 and liver diseases, and its involvement in fatty liver has been reported in in vivo analysis, since PLIN2 is closely related to fat droplet accumulation in the liver." (PMID 38283130, 2024). "Another study indicates that PLIN2 deficiency reduces triglyceride (TG) levels in wild-type mouse embryonic fibroblasts (MEFs) by enhancing autophagy and can prevent fatty liver disease." (PMID 39834787, 2024). "Network analysis identified PLIN2 as a gene associated with fatty liver and cirrhosis, and its expression increased with the increasing number of fat droplets." (PMID 38283130, 2024). "In line with this, the liver-specific loss of perilipin 2, which alleviates hepatic steatosis, was also associated with an increase in MTP." (PMID 33608323, 2021). "PLIN2-knockout mice ameliorate lipid accumulation in the liver and hepatic steatosis and formation of macrophage foam cell, whereas overexpression of PLIN2 causes severe hepatic steatosis." (PMID 34579038, 2021). "Despite consistent reductions in the severity of hepatic steatosis following PLIN2 ablation, the influence of hepatic PLIN2 loss on the development NAFLD comorbidities such as obesity and insulin resistance during disease progression remains unresolved." (PMID 33923083, 2021). "Administering propolis led to decreased Plin2 and Acox expression, which were associated with the mitigation of hepatic steatosis induced by P. gingivalis administration." (PMID 27576340, 2016). "Plin2KO mice chronically fed alcohol are protected from hepatic steatosis, glucose intolerance, and hepatic ceramide accumulation, suggesting a critical pathogenic role of Plin2 in experimental alcoholic liver disease." (PMID 24831094, 2014). "Plin1 is the most abundant PAT protein in adipocytes and Plin2 in the liver, where it has been linked to hepatic steatosis." (PMID 25132820, 2014). "Perilipin 2 (PLIN2) was estimated as the gene most closely associated with fatty liver." (PMID 38283130, 2024). "The PLIN2 gene was found to be associated with ‘fatty liver’ and ‘liver cirrhosis’." (PMID 38283130, 2024). "The expression of PLIN2 was significantly increased in the severe hepatic steatosis group, which means that PLIN2 can mediate the increase in TG content to cause the occurrence of hepatic steatosis in laying hens." (PMID 37568219, 2023). "Indeed, PLIN2, a lipid droplet protein, promotes obesity and progressive fatty liver disease in mice, and loss of PLIN2 lessens diet-induced hepatic steatosis, inflammation, and fibrosis." (PMID 35269515, 2022). "Perilipin 2 association with LDs has been shown to promote LD accumulation by reducing triglyceride turnover, and perilipin 2 knockout mice are protected from hepatic steatosis." (PMID 30477200, 2018). "On the other hand, the loss of PLIN2 has resulted in reduction of liver steatosis and inflammation." (PMID 29196750, 2017). "The association between PLIN2 and plasma aβ may also be due to a host of metabolic disorders, such as fatty liver disease and obesity, which are associated with perilipin-2 and aβ levels." (PMID 28704393, 2017). "The overexpression of perilipin 2 (PLIN2, also known as adipophilin), one of the most abundantly expressed LD proteins, protects LD from autophagy-dependent degradation, while its deficiency stimulates TG catabolism through autophagy, protecting mice against fatty liver diseases." (PMID 32582708, 2020).
Hepatic steatosis (continued). "PLIN2, a known mediator of hepatic steatosis, inflammation, and fibrosis in mice, was increased in both total protein and phosphorylation." (PMID 39605182, 2025). "It is proposed that Seipin balances TG homeostasis, PC synthesis, and Plin2 expression to alleviate hepatic steatosis, providing a promising target for fatty liver disease." (PMID 40799131, 2025). "Immunohisto-chemical evidence confirms PLIN2’s localization on hepatic LD surfaces in fatty liver, suggesting its direct involvement in NAFLD etiopathogenesis." (PMID 41515601, 2025). "Recent studies reported that declining PLIN2 expression in the liver significantly improved high fat diet- and obesity-induced hepatic steatosis, inflammation, and fibrosis by enhancing ATGL-mediated lipolysis, autophagy, and fatty acid β-oxidation." (PMID 40449734, 2025). "Compared with hepatocyte organoids, hepatic steatosis organoids had higher expression of the relevant markers such as perilipin 2 (PLIN2) and fatty acid binding protein 1(FABP1), which indicated the effective establishment." (PMID 39773638, 2025). "Plin2 serves as a well-established marker of LD accumulation and promotes fatty liver disease progression." (PMID 41373932, 2025). "A potent reduction in hepatic steatosis by BPF was confirmed by a strong suppression of an LD-coating protein ADRP/Perilipin 2 in liver specimens as well as by oil red staining, which allows sensitive detection of intracellular TG and cholesterol esters." (PMID 39061835, 2024). "Here, we observed that the treatment for three weeks with a dose of 65 mg/kg BW of TriMetChalc significantly reduced hepatic steatosis in the ob/ob mice, as quantified by histological staining and PLIN2 immunohistochemistry." (PMID 39337328, 2024). "It has been shown before that leucine and isoleucine alleviate obesity- and HFD-induced hepatic steatosis in mice by inducing PLIN2 ubiquitination degradation via activating UBR1/2." (PMID 39426289, 2024). "In the future, it is hoped that the pharmacological suppression of PLIN2 will lead to the development of novel therapies which can be used combat fatty liver disease." (PMID 38283130, 2024). "In the initial stages of NAFL, small LDs begin to accumulate in the cytoplasm and are primarily engulfed by PLIN2, a marker of liver steatosis." (PMID 37958873, 2023). "Taken together, our results show that hepatic expression of Plin2 is more important for coating of hepatic LDs formed upon fasting compared with LDs accumulated as a consequence of diet-induced hepatic steatosis." (PMID 37844775, 2023). "Our analysis suggests that Plin2 is more important for coating of hepatic LDs during fasting as compared with obesity-induced hepatic steatosis." (PMID 37844775, 2023). "A study revealed that dietary essential amino acids ameliorated hepatic steatosis by inducing polyubiquitination of Plin2 in NAFLD mice." (PMID 36779187, 2023). "Perilipin 2 (PLIN2), a lipid droplet protein highly up-regulated in steatotic livers, promotes fatty liver and fibrosis." (PMID 35614477, 2022). "In a rodent model of NASH, hepatic PLIN2 ablation protected against hepatic steatosis and inflammation." (PMID 35740312, 2022). "We determined that diclofenac and other structurally related NSAIDs inhibit CMA by enhanced degradation of LAMP2A in the lysosome, which prevents efficient degradation of PLIN2, leading to cellular lipid accumulation and hepatic steatosis." (PMID 35265214, 2022). "Total and hepatocyte-specific knock-out of perilipin 2 reduced hepatic steatosis in mice fed an obesogenic Western-style diet or a high-fat diet." (PMID 36012215, 2022). "The depletion of perilipin 2 prevents hepatic steatosis via downregulating triglyceride synthesis and LDs accumulation." (PMID 35030992, 2022). "From the current study, the focus is mainly on the role of PLIN2 in liver steatosis, whereas our results bring to light the potential of PLIN4." (PMID 34204055, 2021).
Hepatic steatosis (continued). "In particular, transcripts levels of perilipin 2 – which is essential for the structural integrity of LDs and has been shown to be positively correlated with hepatic steatosis – were substantially decreased." (PMID 33608323, 2021). "High perilipin 2 levels have been described in hepatic steatosis, atherosclerosis, sarcopenia, and some cancers." (PMID 34064680, 2021). "For instance, experimental and clinical data suggest that PLIN2 is involved in the pathophysiology of insulin resistance and type 2 diabetes mellitus, dyslipidemia and fatty liver disease." (PMID 34572396, 2021). "This investigation showed that although both hepatic and extra-hepatic Plin2 are involved in liver steatosis, Plin2 expressed in hepatocytes plays a specific role in immune cell recruitment and fibrogenesis." (PMID 33036257, 2020). "PLIN2, a lipid droplet-coating protein, is related to lipid accumulation in the liver and promotes hepatic steatosis." (PMID 33105604, 2020). "Whole body knockout of PLIN2 decreased the hepatic triglyceride level and protected against diet-induced obesity, and liver steatosis." (PMID 31570772, 2020). "With the current study we demonstrate that the cannabinoid receptor CB1 affected the development of hepatic steatosis by regulating PLIN2 expression in HBs transgenic mice." (PMID 31570772, 2020). "Both the Lsd and Perilipin proteins are known for their physiological roles in modulating lipid content; for example, the Plin1-null mice are lean while the down-modulation of Plin2 alleviates hepatic steatosis." (PMID 31725726, 2019). "We observed that ectopic fat deposition in rodents with diet-induced obesity (DIO) included not only hepatic steatosis but also lipid deposition in circulating monocytes in concert with increased Plin2 expression." (PMID 31754142, 2019). "Lipid droplet associated proteins and their inhibition have become the focus of recent research and the present study evidences exclusive expression of perilipin 2 and 3 in hepatic steatosis with PLIN2 being commonly regulated in-vitro and in-vivo." (PMID 30547786, 2018). "The immunohistochemical analysis showed that PLIN2 localized to the surface of lipid droplets in fatty liver tissues, which indicated that PLIN2 was involved in the progression of fatty liver disease." (PMID 30400205, 2018). "In liver, down-modulation of Plin2 promotes a reduction in hepatic steatosis and increases insulin sensitivity, but a reduction in both Plin2 and Plin3 causes insulin resistance." (PMID 25132820, 2014). "We previously demonstrated a temporal relationship between the development of hepatic steatosis, upregulation of Plin2 and accumulation of hepatic ceramides in alcohol-fed mice." (PMID 24831094, 2014). "PLIN2 null-mice are reportedly protected against diet-induced obesity, adipose inflammation and fatty liver disease." (PMID 24839967, 2014). "The observed effects include alterations in CLD-associated levels of Plin2 and BHMT, both of which are functionally linked to fatty liver formation in mice." (PMID 23874434, 2013). "Additionally, the increase in perilipin (PLIN2) at the proteomic level as well as DAGs and TAGs underscores the increase in de novo lipogenesis and aligns with hepatic steatosis in MASH." (PMID 39605182, 2025). "Furthermore, the human PLIN2-Pro251 overexpression in Plin2 KO mice attenuated high-fat, high-fructose, high-cholesterol diet-induced hepatic steatosis, accompanied by less liver oxidative stress, compared with human PLIN2-Ser251 overexpression." (PMID 40617356, 2025). "Preclinical studies have shown that elevated levels of PLIN2 are associated with several metabolic disorders, including obesity, diabetes, fatty liver disease, atherosclerosis and cardiovascular disease, and inhibiting PLIN2 has been shown to prevent or alleviate these conditions." (PMID 39062220, 2024).
Hepatic steatosis (continued). "It has been found that dietary essential amino acids could ameliorate liver steatosis by inducing polyubiquitination of Plin2, a lipid droplet-stabilizing protein." (PMID 36624524, 2023). "Hepatic expression of Plin2 is enhanced in obese mice and humans with fatty liver disease." (PMID 37844775, 2023). "In contrast to whole-body knock-out, liver-specific PLIN2-deficient mice are not protected against hepatic steatosis when fed a high-fat diet, suggesting a systemic hepatoprotective mechanism of PLIN2." (PMID 36355098, 2022). "Impaired CMA failed to degrade CMA substrates such as PLIN2, which ultimately caused diclofenac-induced hepatic steatosis and toxicity." (PMID 35265214, 2022). "Recently, we showed that a global knockout of the Cb1 gene (Cb1-/-) reduced the expression of the lipid droplet binding protein Perilipin 2 (PLIN2) in the livers of Cb1-/- and hepatitis B surface protein–transgenic mice, which spontaneously develop hepatic steatosis." (PMID 34954190, 2022). "Furthermore, mouse models of PLIN2 deficiency have consistently demonstrated a reduction in hepatic TAG, highlighting the importance of PLIN2 in the development of obesity-associated hepatic steatosis." (PMID 33923083, 2021). "Additionally, PLIN2 knockdown leads to decreasing TG levels, increasing insulin sensitivity, and resistance to fatty liver disease." (PMID 34579038, 2021). "Furthermore, a PLIN2 liver-specific ablation alleviates diet-induced hepatic steatosis and inflammation." (PMID 31570772, 2020). "Knockout of PLIN2 also alleviates diet induced hepatic steatosis." (PMID 33193093, 2020). "Similarly, PLIN3 has a significant role in promoting hepatic steatosis, as elevated levels of both PLIN2 and PLIN3 are reported in both human fatty liver biopsies and animal models of alcohol-related fatty liver disease." (PMID 32585865, 2020). "Moreover, PLIN2 knockout mice are resistant to diet-induced obesity, fatty liver disease and alcohol-induced steatosis, suggesting that PLIN2 is responsible for lipid accumulation, particularly in the liver." (PMID 28454542, 2017). "Additionally, expression levels of Plin2, a marker for hepatic steatosis, as well as Plin3 and Plin4, genes thought to mediate formation of nascent droplets, were also significantly elevated, suggesting increased synthesis and packaging of triglycerides." (PMID 27097220, 2016). "PLIN2 expression has also been shown to positively correlate with the degree of liver steatosis." (PMID 26330055, 2015). "We recently reported that the increase in hepatic Plin2 is twice that of mice fed a control-liquid diet and the upregulation of Plin2 temporally coincides with the onset of hepatic steatosis, glucose intolerance and increase in hepatic ceramides (lipids that can impair insulin signaling)." (PMID 24831094, 2014). "Interestingly, Plin2-null mice are protected from diet-induced obesity and fatty liver disease, indicating a critical role for Plin2 in the development of metabolic diseases." (PMID 25102070, 2014). "Therefore, ameliorating ERS to enhance PPARγ and promote lipolysis of LD mediated by Plin2 and Plin5 may be an effective way to prevent hepatic steatosis." (PMID 41373932, 2025). "Moreover, a decreased PLIN2 expression has been shown to reduce liver steatosis." (PMID 39337328, 2024). "Because perilipin 2 is known to promote lipid droplet accumulation via inhibiting lipolysis, it is possible that the change in lipid droplet phospholipid composition observed in ethanol-fed rats drives the development of hepatic steatosis through perilipin 2 recruitment." (PMID 38021172, 2023). "Studies have demonstrated that both Plin2 and Plin5 are significantly upregulated in mice with HFD-induced hepatic steatosis and in patients with fatty liver." (PMID 41373932, 2025). "It is then understandable that PLIN2 was found to be upregulated in patients with NAFLD and its ablation improved hepatic steatosis." (PMID 37344835, 2023).